CAT (catalase)
Diseases named in the same sentence as CAT in open-access papers (continued):
Sharing a sentence is not in itself a finding about the gene and the disease.
Hypercholesterolemia (23 papers, 2010 to 2025). An increased concentration of cholesterol in the blood. "Hypercholesterolemia causes alterations in cholesterol and triglyceride metabolism, weakening enzymes like catalase and superoxide dismutase, creating more ROS, which leads to more lipid peroxidation." (PMID 39825321, 2025). "Other authors reported the OS in subclinical hypothyroidism, as shown by reduced aryl-esterase and increased TBARS and CAT, but they attributed this pattern to hypercholesterolemia." (PMID 40429666, 2025). "The hypercholesterolemic condition in the PG group caused significantly lower antioxidant status (TAS) and antioxidant enzymes (SOD, GPx, and CAT) than NG group (p < 0.05) thus proving the link between hypercholesterolemia and oxidative stress." (PMID 33202660, 2020). "In fact, the lipid peroxidation levels increased with decrease in SOD, CAT and GPx levels in heart, liver and kidney due to hypercholesterolemia." (PMID 26648825, 2015). "Studies have shown that hypercholesterolemia diminishes the effectiveness of the antioxidant defense system and decreases the activities of CAT and SOD in rats." (PMID 23243438, 2012). "In vivo, CPP20 enhanced the activity of antioxidant enzymes (CAT, SOD, and GSH-Px) and regulated TC, TG, LDL-C, HDL-C, and TBA levels in the serum and liver to relieve symptoms of hypercholesterolemia." (PMID 39123535, 2024). "The results of this study are consistent with the results of previous studies, CPP20 increased the levels of SOD, CAT, and GSH-Px, reduced the level of MDA in the liver, and alleviated hypercholesterolemia by enhancing the antioxidant function." (PMID 39123535, 2024). "A study has shown that hypercholesterolemia diminishes the antioxidant defense system and decreases the activities of SOD and CAT, which elevates the lipid peroxide content." (PMID 32110925, 2020). "Hypercholesterolemia induced a decrease in serum superoxide dismutase (SOD), catalase, reduced glutathione (GSH) and an increase in malondialdehyde (MDA) levels that were ameliorated by karela administration." (PMID 28623919, 2017). "Earlier report also demonstrates that hypercholesterolemia diminishes the antioxidant defense system and decreases the activities of SOD and catalase in rats." (PMID 27840607, 2016). "Studies have shown that hypercholesterolaemia diminishes the antioxidant defense system and decreases the activities of SOD and CAT in rats." (PMID 27695419, 2016). "There were significant increase in GSH, CAT and SOD by Monodora myristica extract in this study, the extract ameliorated oxidative stress induced by hypercholesterolemia due to its flavonoid and polyphenol content." (PMID 26199582, 2015). "The silymarin treatment improved liver function by decreasing the levels of aspartate aminotransferase (AST), alanine aminotransferase (ALT), superoxide dismutase/catalase (SOD/CAT), thiobarbituric acid reactive substances (TBARSs), hypertriglyceridemia, and hypercholesterolemia." (PMID 40289935, 2025). "Hypercholesterolemia leads to a decrease in SOD and catalase levels." (PMID 31931807, 2020). "The induction of hypercholesterolemia resulted in increased lipid peroxidation, as indicated by elevated MDA levels and reduced activity of the antioxidant enzymes catalase, SOD, and GSH, in comparison to the negative control group." (PMID 41031162, 2025).
ovarian carcinoma (23 papers, 2008 to 2025). A malignant neoplasm originating from the surface ovarian epithelium. "In this preliminary study we were able to show that a specific CAT SNP is associated with poor survival in ovarian cancer patients." (PMID 26301412, 2015). "Specifically, low serum CAT levels were associated with adverse prognosis for ovarian cancer." (PMID 26301412, 2015). "This study indicates a strong association with the catalase SNP and survival of ovarian cancer patients, and thus may serve as a prognosticator." (PMID 26301412, 2015). "The cytotoxicity induced by high-dose ascorbate in ovarian cancer cells can be effectively reversed by catalase, a specific H2O2 scavenger, suggesting the crucial role of oxidative stress in ascorbate-induced cell death in ovarian cancer cells." (PMID 38790722, 2024). "Urinary catalase, α-1 Acid Glycoprotein and Peroxiredoxin-2 can be useful biomarkers for early detection and treatment response of ovarian cancer." (PMID 33137912, 2020). "It has been shown that Catalase antioxidant enzyme enhances the survival of detached breast/ovarian cancer cells and helps their successful metastasis." (PMID 33137912, 2020). "In conclusion, urinary micro-peptides [Catalase, α-1 Acid Glycoprotein and Peroxiredoxin-2] can be useful biomarkers for early detection and treatment response monitoring of ovarian cancer." (PMID 33137912, 2020). "The lower level of Catalase in ovarian cancer patients was recorded (2.41±1.01 μmol/mol) vs controls (4.27±0.73 μmol/mol)." (PMID 27902750, 2016). "Of the SNPs studied when examining survival, we found the CAT SNP (rs1001179) to be a significant predictor of death when present in ovarian cancer patients as illustrated by the Cox regression and K-M survival analyses." (PMID 26301412, 2015). "To determine further the relevance of FOXO1 target genes in ovarian cancer cells, we also compared the levels of p27Kip1, MnSOD, catalase and GADD45α expression in KF28, KFr13 and KFr13Tx cells by western blotting." (PMID 18319717, 2008). "Afterward, univariate Cox regression analysis was performed to evaluate the prognostic value of each tryptophan metabolism-related gene in the TCGA ovarian cancer cohort, with IDO1, ALDH3A2, HADHA, OGDHL associated with risk values, and CAT, WARS1 involved in protective factors." (PMID 38468343, 2024). "Similarly, in A2780 ovarian cancer cells, AgNPs decreased the activity of CAT and SOD enzymes and the level of glutathione." (PMID 38410788, 2024). "Moreover, only the expressions of MMP7, MMP12, TIMP3, CAT and Nrf2 were affected by the clinical stage of ovarian cancer." (PMID 38397798, 2024). "To test whether oxidative stress play a role in VC F7 inducing the antiproliferative effect against ovarian cancer cells, we measured the levels of lipid peroxidation, catalase, and glutathione peroxidase in OVCAR-3 cells." (PMID 32580345, 2020). "However, a catalase SNP was identified as a predictor of ovarian cancer survival by the Cox regression model." (PMID 26301412, 2015). "In ovarian cancer cells, QUE enhanced the CIS sensitivity of the CIS-resistant cell line SKOV-3/CIS by inhibiting the expression of SOD2, catalase (CAT), GPX1, HO-1, Nrf 2, and PI3K/Akt/mTOR." (PMID 40491926, 2025). "The activity of GPx was insignificantly higher in healthy controls, while the SOD and CAT activities, as well as TAC, were slightly higher in the women with ovarian cancer (p > 0.05)." (PMID 34279378, 2021). "The activity of two major antioxidative enzymes, that is, superoxide dismutase (SOD) and catalase (CAT), was measured in ovarian cancer cells exposed to RVT and 3,3′,4,4′-THS in order to assess their protection against oxidative stress." (PMID 26229578, 2015). "Furthermore, CAT-loaded and HER-2 nanobody-conjugated nanoparticles have shown tremendous potential for ovarian cancer therapy." (PMID 37273798, 2023). "XOR, CAT, SOD, and GPx expression is decreased in patients with ovarian cancer." (PMID 34822465, 2021).
ovarian carcinoma (continued). "Stress variables (MDA, AGEs, AOPPs, NO), profile of antioxidants (SOD, Catalase, Vitamin E & A, GSH, GRx, GPx) and inflammatory biomarkers (MMP-9, MMP-2, MMP-11, IL-1α and TNF-α) were biochemically assessed from venous blood of fifty ovarian cancer patients and twenty healthy control subjects." (PMID 27902750, 2016).
acute kidney injury (22 papers, 1998 to 2025). Sudden and sustained deterioration of the kidney function characterized by decreased glomerular filtration rate, increased serum creatinine or oliguria. "CAT rs769217 has been shown to be associated with hospital morbidity and mortality in the Turkish population with acute kidney injury." (PMID 37698290, 2023). "Moreover, effects on in vivo oxidative and inflammatory markers (e.g., glutathione peroxidase, superoxide dismutase, catalase, and C-reactive protein) should also be evaluated in animal models, as oxidative stress is mainly responsible for renal failure." (PMID 30991760, 2019). "The diclofenac-induced acute kidney injury in rats also showed increased levels of MDA and decreased GSH, TAC, and CAT." (PMID 38911247, 2024). "Further, the proportion of patients in the non-CAT group was significantly higher than that in the CAT group due to insufficient adjustment for AST-120, which inhibits renal failure progression in the two groups." (PMID 37198559, 2023). "In this study, MDA, SOD, CAT and GSH activities were among the decision lines in patients with chronic and acute renal failure according to the ANOM test." (PMID 35720997, 2022). "Previous study also support this notions that amla extract is capable of restoring the antioxidant enzymes such as catalase and SOD activities in acute kidney injuries." (PMID 32724620, 2020). "Observable depletion in the antioxidant ability was identified in the cisplatin-induced acute kidney injury group, as demonstrated by the significant reduction in GSH, SOD, and CAT levels compared to the control animals." (PMID 33126443, 2020). "Also, LC can improve the antioxidant enzyme activity, including CAT and GSH, and reduces the MDA concentration in renal tissues in acute renal failure induced by myoglobinuric in rats." (PMID 33117167, 2020). "All groups were compared with each other according to renal failure findings and enzyme activities, such as Xanthine oxidase (XOD), Superoxide Dismutase (SOD) and Catalase in renal cortex and Glutathione Peroxidase (GSH-Px), in blood at 3rd day after ischemia and reperfusion." (PMID 9515237, 1998). "Acute kidney injury (AKI) was accompanied by significant oxidative derangements, as evidenced by increased MDA and NO levels and decreased antioxidant defenses (GSH, SOD, CAT, and GPx activities)." (PMID 41465610, 2025).
anemia (20 papers, 2010 to 2025). A reduction in the number of red blood cells, the amount of hemoglobin, and/or the volume of packed red blood cells. "These simulations add further support to the proposed model of CaT remodeling in iron-deficiency anemia." (PMID 30779710, 2019). "Iron deficiency affects activity of many iron-dependent enzymes (like catalase), and in iron deficiency anemia (IDA) RBCs are more susceptible to oxidation." (PMID 26527217, 2015). "Oxidative stress is increased in anemia, perhaps particularly in iron-deficiency anemia where iron-deficiency affects catalase activity." (PMID 22906142, 2012). "In a mouse model of iron-deficiency anemia, the A. membranaceus polysaccharide-iron (III) complex showed a faster rise in hemoglobin, superoxide dismutase, and catalase levels, along with a quicker decrease in methane dicarboxylic aldehyde levels." (PMID 39652245, 2024). "An iron supplement test in the iron-deficiency anemia mouse model, showed that the APS-iron (III) complex can quickly supplement iron, increase SOD and CAT activity, and reduce the normal MDA level." (PMID 33503027, 2021). "In the rapidly progressive model of PKD, RC/null mice, overexpressing mitochondrial-targeted catalase mitigated cyst progression, the development of uremia, and severe anemia." (PMID 34671066, 2021). "Our study detected more pronounced decrease in antioxidant biomarkers (SOD, GPx and catalase) in dogs with moderate anaemia compared to those with mild anaemia." (PMID 28438201, 2017). "GSH, CAT, and superoxide are naturally occurring compounds in erythrocytes, contributing to the antioxidant capacity of the blood, and reducing their cellular levels, as seen in anemia, results in oxidative stress and, subsequently, HA." (PMID 38089915, 2023). "The results of a human study including 33 female iron-deficient anemia patients performed in order to analyze the redox status showed that the activity of catalase and the total antioxidant capacity in the anemia group were significantly lower than in the controls." (PMID 35631204, 2022). "Furthermore, this study detected more pronounced decrease in antioxidant biomarkers (SOD, GPx and catalase) in dogs with moderate anaemia compared to those with mild anaemia." (PMID 28438201, 2017). "The induction of anemia with PHZ significantly increased the levels of TBARS and the activities of SOD and CAT in hepatic tissues compared to the normal animals." (PMID 39086862, 2024). "A significant (P < 0.05) increase in the MDA and NO concentrations in the anemia group was observed, while GSH, CAT, and GST levels were reduced compared to the control group." (PMID 38089915, 2023). "Furthermore, considering the severity of anaemia, the activities of SOD, GPx and catalase were significantly lower (P < 0.01) in moderately anaemic dogs compared to mildly anaemic." (PMID 28438201, 2017). "Decreased activity of catalase may lead to increased H2O2 concentration and damage of oxidation sensitive tissues that may contribute to the manifestation of various diseases such as diabetes mellitus and anemia." (PMID 26527217, 2015).
chronic granulomatous disease (20 papers, 2014 to 2025). Chronic granulomatous disease (CGD) is a rare primary immunodeficiency, mainly affecting phagocytes, which is characterized by an increased susceptibility to severe and recurrent bacterial and fungal infections, along with the development of granulomas. "Chronic granulomatous disease (CGD) is an inborn error of immunity (IEI) that is characterised by recurrent infections caused by catalase-positive bacteria and fungi, such as Staphylococcus aureus and Aspergillus species." (PMID 35140711, 2021). "Chronic granulomatous disease (CGD) is a phagocyte defect associated with a marked susceptibility to certain bacteria (catalase positive) and fungi." (PMID 30275850, 2018). "Mutations in components of the NADPH oxidase complex—such as CYBB, encoding the catalytic subunit gp91phox—cause chronic granulomatous disease (CGD) in both humans and mice, leading to recurrent infections with catalase-positive bacteria and fungi." (PMID 40928289, 2025). "Chronic Granulomatous Disease (CGD) is caused by genetic defects in the phagocyte NADPH oxidase leading to potentially severe infections with catalase positive micro-organisms." (PMID 30984725, 2019). "Loss of NOX2 activity results in a disease called chronic granulomatous disease (CGD), characterized by an increased susceptibility to infections with fungi and with a subset of catalase‐positive bacteria." (PMID 28076662, 2017). "Chronic granulomatous disease (CGD) is an IEI with impairment of the phagocyte respiratory burst, causing susceptibility to catalase-positive bacteria and fungi." (PMID 38068532, 2023). "Chronic granulomatous disease (CGD) is a rare inherited disorder of the innate immune system caused by mutations in any of the genes encoding subunits of the superoxide-generating phagocyte NADPH oxidase, which is essential for killing catalase-producing bacteria and fungi." (PMID 24947584, 2014). "Burkholderia cepacia is a catalase-positive, aerobic, lactose-producing, gram-negative bacillus that commonly affects patients with immunodeficiency, with specific predilection to patients with cystic fibrosis and chronic granulomatous disease." (PMID 39544580, 2024). "However, the chronic granulomatous disease is characterized by infections with fungi producing catalase because they are not killed by neutrophils." (PMID 36365006, 2022).
glaucoma (19 papers, 2010 to 2025). Increased pressure in the eyeball due to obstruction of the outflow of aqueous humor. "Catalase has been known to be active in the calf trabecular meshwork, and single-nucleotide polymorphisms in the catalase gene have been linked to primary open-angle glaucoma in Chinese populations." (PMID 40650044, 2025). "To Investigate whether the g.4760C>T polymorphism in the promoter region of the catalase gene (CAT) is a risk factor for primary angle closure glaucoma (PACG) in the Saudi population." (PMID 23961996, 2013). "SOD, GPx, and CAT, three common antioxidative markers, were found to be increased in the aqueous humor of glaucoma patients in meta-analyses conducted in 2016 and 2019." (PMID 35163178, 2022). "In the DEX-induced glaucoma control group, the levels of antioxidants, such as CAT, SOD, GPx, and GSH, were found to be decreased notably as compared to the normal group (p < 0.001)." (PMID 35252223, 2021). "Thus, the reduced catalase expression of TFs represents a weak point that potentially opens up new therapeutic options for IOP-lowering glaucoma surgery." (PMID 40173140, 2025). "It is well-documented that IOP increase in glaucoma induces oxidative stress in RGCs, and cells are protected from these effects of ROS by antioxidant enzymes, including superoxide dismutase, catalase, and glutathione transferase, and small molecule antioxidants such as glutathione." (PMID 37793503, 2023). "Moreover, gene therapy with SOD2 and catalase decreases RGC death in a mouse model of glaucoma (optic nerve crush)." (PMID 30373222, 2018). "It’s possible that the link between mitochondrial abnormalities and/or oxidative stress and glaucoma are not linked through the catalase pathway and that other oxidative stress pathway(s) may be involved." (PMID 23961996, 2013). "Treatment with γ-oryzanol showed a significant protective antioxidant effect against oxidative stress in the glaucoma model for raising the down-regulated SOD, CAT, and GPx levels in this model." (PMID 34636986, 2022). "The control group had significantly increased MDA and LDH levels and significantly decreased GPx, CAT, and SOD levels, indicating that the glaucoma rats had high oxidative stress levels." (PMID 33456358, 2021). "It is uncertain whether enzymatic antioxidants, including CAT, SOD, and GPx, increase or decrease in the serum of glaucoma patients, according to the 2016 meta-analysis study." (PMID 35163178, 2022).